EGFR (epidermal growth factor receptor)
Diseases named in the same sentence as EGFR in open-access papers (continued):
Sharing a sentence is not in itself a finding about the gene and the disease.
cancer (continued). "However, only AKT1, EGFR, BCL2, HSP90AA1, and PTGS2 exhibited strong binding affinities with pomegranate compounds, which are significantly declared in affected cells to enhance cancer progression." (PMID 40573291, 2025). "Therefore, in light of CD73’s role in cancer cell survival and progression, it would be insightful to explore whether inhibiting CD73 in combination with the EGFR inhibitor tyrphostin AG1478 could enhance therapeutic responses in a GB in vitro model." (PMID 40191718, 2025). "The epidermal growth factor receptor (EGFR) is a potent oncogene that can activate survival, migration, and proliferation pathways, and clinical data suggests it may also play an immunomodulating role in cancers." (PMID 39521886, 2025). "Thus, co-targeting EGFR and other molecules might be a promising strategy to overcome TKI resistance in cancer." (PMID 40231269, 2025). "They found that shortly after treatment, some cancer cells enter a quiescent state with low KRAS activity, while others bypass inhibition by producing newly synthesised KRASG12C, which is maintained in an active, drug‐insensitive state via EGFR‐ and AURKA‐driven signalling." (PMID 41025426, 2025). "Else, PRSS22 was found to be not expressed in cancer cells (EGFR/FGFR2/MET/VEGFR) of GC patients." (PMID 41497316, 2025). "The activation of the epidermal growth factor receptor (EGFR), a type of receptor tyrosine kinase that is overexpressed in GBM,99,100 results in the activation of multiple downstream signal transduction pathways related to cancer progression, including the PI3K/AKT/mTOR pathway." (PMID 40527011, 2025). "The underlying mechanisms may be that SMET12 specifically binds to EGFR on the surface of cancer cells and CD3 on the surface of lymphocytes to trigger spatial locations of effector T cells near cancer cells and the subsequent generation of immunological synapse, thus activating effector T cells." (PMID 41583476, 2025). "In addition, evidence is emerging that EGFR has a number of non-canonical kinase-dependent and kinase-independent roles that promote cancer cell survival." (PMID 40003864, 2025). "In cancer, cells exposed to genotoxic stressors—including chemotherapy, radiation, or oxidative damage—are more likely to accumulate and retain eccDNAs that harbor amplified oncogenes, drug resistance elements, or stress-response regulators such as HSP90, EGFR, and MYC." (PMID 40521196, 2025). "Epidermal growth factor receptor (EGFR), prostate-specific membrane antigen (PSMA), and human epidermal growth factor receptor 2 (HER2) have emerged as three prominent targets for MAB-functionalized NPs in cancer therapy, which have been extensively investigated in recent years." (PMID 40448105, 2025). "Targeted therapies, such as anti-epidermal growth factor receptor (anti-EGFR) and anti-vascular endothelial growth factor (anti-VEGF) monoclonal antibodies, have shown promise in patients with KRAS/NRAS wild-type tumors and microsatellite instability-high (MSI-H) cancers." (PMID 40426943, 2025). "It is important to note that although EGFR is found on the surface of cancer cells, its presence in normal tissue such as the skin, lungs, and kidneys creates a challenge for targeting the protein to treat cancer." (PMID 40071065, 2025). "Moreover, luteolin effectively limits the expression levels of many proteins including extracellular signal‐regulated kinase (phosphorylated (p)‐Erk1/2), epidermal growth factor receptors, (p‐EGFR and p‐Akt), and activator of transcription and signal transducer (p‐STAT3) in cancer cells." (PMID 39830909, 2025).
cancer (continued). "Together, these data demonstrate an unanticipated requirement for non-canonical EGFR signaling in cancer cell extrusion, which might act in part by promoting E-cadherin endocytosis." (PMID 41132131, 2025). "The findings indicate that the sensitivities to EGFR inhibitors (afatinib, erlotinib, and gefitinib) and MAPK inhibitors (doramapimod) were significantly greater in the high-MLRS group, indicating the potential importance of these agents in inhibiting the progression of malignant tumors." (PMID 40535574, 2025). "However, the positive prognosis correlation of BLCA with Hub-EGFR.Sig observed in this study was not consistent with that in pan-cancer, although both DSS and PFI in BLCA showed the strongest association with Hub-EGFR.Sig." (PMID 40574864, 2025). "KEGG pathway enrichment results demonstrated that core target genes were enriched in signaling pathways including PI3K/Akt, Proteoglycans in cancer, AGE/RAGE, and EGFR, suggesting that CS could exert its anti-RIF effect by targeting these biological processes and signaling pathways." (PMID 41142245, 2025). "In addition, oncogenic signals such as epidermal growth factor receptor (EGFR) activation, certain and TH1 cytokines such as IFN-γ and TNF-α also induce its expression in cancer cells as well as in non-cancer cells (such as fibroblasts and myeloid cells) in the TME." (PMID 40109334, 2025). "The epidermal growth factor receptor (EGFR) is a critical regulator of multiple oncogenic signaling cascades, including MAPK, PI3K/AKT/mTOR, and JAK-STAT pathways, which collectively contribute to enhanced proliferation, angiogenesis, and resistance to apoptosis in cancer." (PMID 41449180, 2025). "It was found that T790M mutation is the common mechanism of resistance against gefitinib and afatinib indicating that those two drugs may not be effective in EGFR T790M-positive cancers." (PMID 38888847, 2025). "Hence, CWI1-2, by targeting the endogenous IGF2BP2/EGFR/PI3K/AKT axis, represents a novel therapeutic approach that overcomes EGFR-targeted resistance attributed to both autonomous and non-cell-autonomous interactions between cancer cells and CAFs." (PMID 40362183, 2025). "Interaction between CAFs and cancer cells is mediated with a complex signaling network that consists of signaling pathways for TGFβ, mitogen-activated protein kinase (MAPK), Wnt/β-catenin pathway, JAK/STAT pathway, epidermal growth factor receptor (EGFR), and NF-κB." (PMID 40165901, 2025). "Furthermore, combined treatment with the EGFR/STAT3 inhibitor AG490 resulted in additional reduction of invasive cell numbers, demonstrating enhanced inhibitory effects on cancer cell migration and invasion when curcumin was administered in combination with AG490." (PMID 41312415, 2025). "Notably, high expression of EGFR was observed in 22.4% of cancer tissues, while no high expression (0%) was found in normal tissues." (PMID 40236691, 2025). "While early-stage cancer detection using liquid biopsy remains challenging, it can complement tissue testing by identifying actionable mutations like KRAS and EGFR even in non-metastatic and locally advanced stages, guiding personalized treatment in a timely manner." (PMID 40282516, 2025). "Despite the fact that EGFR is overexpressed in numerous carcinomas and thus represents a promising target for therapeutic intervention, mutations of the PI3-kinase or K-Ras result in a lack of response to conventional anti-EGFR therapy." (PMID 40761247, 2025). "EGFR-mediated signaling is overexpressed in various cancer cells but not normal cells." (PMID 38745775, 2024). "We examined whether BEC-secreted factors promote EGFR activation and whether there were differences between parental and brain homing MB-MDA-231 cancer cells that may account for the ability of MB-MDA-231/Brain cells to respond to BEC-secreted factors via cellular elongation." (PMID 38762624, 2024).
cancer (continued). "APC-labelled anti-CD45mAB was used to gate remaining hematogenous cells, while multiple epithelial markers (EpCAM, EGFR, and Pan-Cytokeratin) and an epithelial–mesenchymal transition (EMT) marker (Vimentin) labelled with fluorescein isothiocyanate (FITC) were used to sort cancer cells." (PMID 38469233, 2024). "Thus, suppression of EGFR signaling is a shared property of EML4-ALK(V1)+ cancer cells and depends on oncogene activity, but is not a general property of oncogenic ALK receptor activity." (PMID 39488530, 2024). "Sequencing results showed that MET, EGFR, KMT2B and RET gene were mutated in LGFM, and KMT2B gene had cancer promoting effect, but there was no literature report in LGFM, which may be of certain significance for the diagnosis and treatment of LGFM." (PMID 38347522, 2024). "However, unlike other EGFR-driven cancers, targeting this receptor in TNBC yields inconsistent therapeutic responses." (PMID 38605363, 2024). "By constructing pro-TCEs that contain peptide masks tethered to the TAA binding site through cancer protease-cleavable linkers, several companies are testing masked TCEs against EGFR, HER2 and PSMA, TAAs that have not been amenable to safe TCE targeting in the past due to off-target or CRS toxicity." (PMID 39606234, 2024). "Cancer Research UK, however, was able to randomize 272 patients with potentially resectable liver metastases into either periOP FOLFOX alone as the standard treatment or FOLFOX plus the EGFR inhibitor cetuximab as the experimental arm with PFS comparison as the primary endpoint." (PMID 38473219, 2024). "Furmonertinib, a novel third-generation EGFR-TKI, has shown promise in overcoming drug resistance mediated by the ATP-binding cassette transporters ABCB1 and ABCG2, which are central to the development of multidrug resistance in cancer patients receiving conventional chemotherapy." (PMID 39743996, 2024). "The survival benefit was statistically significant in the left-sided cancer cohort, but we could not demonstrate a benefit when patients with right-sided cancers received EGFR mAbs." (PMID 38402342, 2024). "We speculate that the presence of these alternative pathways is the reason why invasive aspergillosis is not even more common in cancer patients treated with EGFR inhibitors." (PMID 39314401, 2024). "In addition, significant differences in gene expression were observed by RNA-seq analysis when comparing transcriptional profiles of acutely treated cells (48 hours), DTPs, and cells exhibiting acquired resistance across EGFR-mutant and ALK fusion-positive cancer cell lines under therapy." (PMID 38702301, 2024). "Moreover, the derivative II illustrated powerful cytotoxicity against colorectal HCT-116, SW480, ovarian SKOV3, glioblastoma U87 and breast SKBR3 cancer cell lines, with IC50 values ranging from 3.83 to 11.94 μM when compared to erlotinib through EGFR inhibition behavior." (PMID 38474579, 2024). "Thus, it is not surprising that EGFR inhibitors improved clinical outcomes in cancers driven by the activation of FGFR signaling." (PMID 39272961, 2024). "EGFR and MAPK signaling pathway components as well as the EMT transcription factor SLUG (SNAI2;) or the putative cancer stem cell marker CD44 may be considered, at least partially, as effective cancer targets or surrogate biomarkers." (PMID 38378518, 2024). "Indeed, although PDGFRB mutations are not often mentioned, EGFR and ERBB2 are involved in cancer research and targeted treatment." (PMID 39678505, 2024). "However, the role(s) of these EGFR inhibitors in regulating the genes and proteins involved in apoptosis and oncogenesis is not well studied in any of the cancer types, including CRC." (PMID 37183661, 2024). "The growth and progression of many cancers, including CRC, could be driven by EGFR." (PMID 39000238, 2024).
cancer (continued). "Interestingly, these mechanisms can coexist in the same cancer, suggesting that a combination of ALK and EGFR inhibitors could potentially be an effective treatment for certain NSCLC patient subsets." (PMID 38927911, 2024). "While both EGFR and HER2 are excellent targets and a number of targeted therapies have been successfully transformed to the clinic for patients with EGFR- or HER2-mutated NSCLC, there is no Food and Drug Administration (FDA)-approved HER3-targeted therapy for cancer treatment." (PMID 39337530, 2024). "Conversely, we found no loss of ERBB2, EGFR, ABL1, RELA, and RELB transcript in c-MYC-destabilized cells compared to controls, and the 3′UTRMYC1-18-treated cancer cells tended to restore MYC expression towards the normal female mammary epithelial expression levels." (PMID 39123391, 2024). "However, 2D5 exerted inhibitory effects on murine cancer-cell lines (such as B16-F10, E0071, and EL-4) and human EGFR-negative cell lines [such as human T (Jurkat) and keratinocyte-like (HaCaT) cell lines]." (PMID 38745775, 2024). "In our study, we applied the VS study using EGFR-TK receptor-gefitinib complex structure against a diversity set of 350,000 small-molecule compounds (ChemDiv Library DC0, accessed Sep 08, 2022) in order to identify new EGFR inhibitors as potential anti-cancer agents." (PMID 38625872, 2024). "Sex-specific differences are observed in the efficacy of certain treatments, including epidermal growth factor receptor (EGFR) inhibitors in NSCLC and rituximab (a CD20 monoantibody) in NHL, which go beyond the general disparities in survival between sexes in these two cancers." (PMID 38594230, 2024). "In addition, the heterogeneity of KRAS‐mutant cancers leads to limited efficacy of KRAS inhibitors (KRASi) as monotherapy; while their combination with other targeted agents, including SHP2, EGFR, PD‐L1, CDK4/6, PLK1, and IRE1α, significantly enhances anti‐tumor activity and overcomes resistance." (PMID 39254172, 2024). "However, whether used in monotherapy or combination with chemotherapy, ICIs appear to be ineffective in EGFR, ALK, RET, and HER2 driver gene‐positive cancers." (PMID 39184861, 2024). "Therefore, lncRNA H19 may play a key role in the response of cancer cells, such as NSCLC, to EGFR-TKIs." (PMID 38200584, 2024). "Similarly, an open-label, non-comparative, multicentre, phase II trial of 46 cancer patients treated with the EGFR inhibitor erlotinib showed that EGF ointment was effective in treating 69.2% of patients." (PMID 39061166, 2024). "Moreover, miR-646 inhibits cancer development by downregulating oncogenes, such as FOXK1 and EGFR." (PMID 39519267, 2024). "Finally, EGFR, CREB, and serum/tissue copper depletion are all targets in anti-cancer treatments." (PMID 39138174, 2024). "For example, one of the consequences of HER2 overexpression in cancer could be the elevation of the otherwise non-optimal heterodimers with EGFR, resulting in potentiation of oncogenic signaling." (PMID 38498590, 2024). "On the other hand, cancer samples from TCGA Pan Cancer Atlas Studies harboring high CN increase of CBX3 display enhanced expression of EGFR at the transcriptional level, further confirming the tight relationship between the CNVs occurring in CBX3 and EGFR genes in human cancer." (PMID 37633946, 2023). "Thus, the O‐glycosylation sites on EGFR and MET initiated by GALNT2 could vary in different cancer types, which leads to differential effects of GALNT2 on the activities of EGFR and MET." (PMID 36409270, 2023). "Thus, multiple mechanisms may link cholesterol levels to EGFR/PI3K/Akt/mTOR signaling in HNSCC and other cancers." (PMID 37568764, 2023).
cancer (continued). "Collectively, these findings indicate that the simultaneous overexpression of CBX3, RAC1 and EGFR could lead to a negative synergistic effect on cancer patient survival." (PMID 37633946, 2023). "All this information helps to conclude that although EGFR wild-type cancer cells survival may not be dependent on EGFR’s kinase activity, it may be sustained by EGFR without involving its kinase activity." (PMID 37446288, 2023). "We utilized database analysis, cancer cell assays and PDX models and revealed that SYK stratification consistently enriched the population of patients predicted to be responsive to EGFRis and ALKis among those with EGFR-mutant and ALK-translocated NSCLC, respectively." (PMID 37183231, 2023). "In situations wherein HER2 is highly overexpressed at the plasma membrane of certain cancer cells, the accumulation of transient interactions exerted by large numbers of HER2 molecules is likely sufficient to influence the membrane dynamics and endocytosis of EGFR." (PMID 36781849, 2023). "Therefore, along with the EGFR, the EGF is also considered a potential target for cancer therapy." (PMID 37241784, 2023). "Interestingly, IFIT1 and IFIT3 genes are upregulated during cancer metastasis and invasion and mediate their growth-promoting actions by complexing and phosphorylating Hsp90 and its client proteins, including PKC, EGFR, Akt, and p38." (PMID 36766731, 2023). "Hence, CARNIVAL was able to construct a signalling network highly enriched for HER2 signalling, including the signalling proteins MAPKs, ESR1, ERBB2, EGFR, PIK3CA and EP300, which are known to be relevant for the primary mechanism of action of lapatinib in HER2 + cancers." (PMID 37715141, 2023). "Despite many studies evaluating the role of perioperative EGFR–TKIs, the patient pool with stages IB–IIIA represents a very wide variety of cancers with inconstant prognosis, which may limit the application of these results to resected stage III EGFR-mutant adenocarcinoma." (PMID 37697233, 2023). "EGFR Tyrosine kinase inhibitors (TKIs) can enhance the effect of MHC class I and II antigens on IFN-γ to increase CD8+T cells and DC cells levels, eliminate FOXP3+Tregs, inhibit Macrophage polarization to M2 phenotype, and reduce the PD-L1 expression in cancer cells." (PMID 37799727, 2023). "Some well-known signaling pathways, such as MAPK, EGFR/HER, CDK, and Cadherin–catenin complex, are major cell cycle players and deregulation of their phosphorylation–dephosphorylation activity has been shown to lead to the formation of various types of cancers." (PMID 36997065, 2023). "It remains to be understood whether alternative oligomer structures carry out different functions in the cell, and whether thy coexist and/or cooperate, for example, to build larger architectures, such as the poorly characterised μm‐length EGFR clusters reported by STORM in normal and cancer cells." (PMID 36282005, 2023). "Retrospectively, information of 88 patients receiving EGFR-TKIs as first-line targeted treatment or in combination with SFI in the Affiliated Drum Tower Hospital of Nanjing University Medical College and the Affiliated Cancer Hospital of Anhui University of Science and Technology was collected." (PMID 36008690, 2023). "CD44, and particularly the CD44v isoform, functions as a marker for cancer stem cells (CSCs) not only due to its unique expression on the cell surface, but also, and more significantly, because of its potent role in regulating various CSC properties, partly via EGFR-mediated pathways." (PMID 37958796, 2023). "However, comprehensive studies of the roles of EGFR and EGFR inhibitors (TKIs) in cancer and AD are not available." (PMID 37601068, 2023). "Hence, the EGFR & VEGFR-2 inhibitory signaling pathway has become a crucial strategy for the identification and development of novel therapeutics for a variety of human malignancies for the treatment of cancer trauma." (PMID 37501139, 2023).